MMP12 (matrix metallopeptidase 12)
Diseases named in the same sentence as MMP12 in open-access papers (continued):
Sharing a sentence is not in itself a finding about the gene and the disease.
tumor (continued). "Even so, while MMPs commonly facilitate tumor progression, MMP12 displays a controversial role in cancer progression." (PMID 25003596, 2014). "In these experiments we also demonstrated that the MMP12-dependent anti-tumor and anti-angiogenetic activity were related to the presence of the truncated form of uPAR." (PMID 25003596, 2014). "We previously demonstrated that the full length uPAR is required to perform invasion and that uPAR cleavage by the matrix metalloproteinase 12 (MMP12) strongly decreased uPAR-dependent invasion of tumor cells and endothelial cells." (PMID 25003596, 2014). "MMP12 can be employed in the field of “targeted therapies” as a biological drug to be delivered directly in patient's tumor mass." (PMID 25003596, 2014). "CM-ECFC-MMP12 impaired the invasion of A375 as well as the capillary morphogenesis of HMVEC when compared to CM-ECFC-MOCK, confirming a MMP12-dependent anti-tumor and anti-angiogenic activity, as it was reverted by anti-MMP12 antibody." (PMID 25003596, 2014). "In fact, despite evidences about correlation of tumor MMP12 with poor prognosis in several tumors, there are growing evidences about the “protective role” of MMP12, in tumor progression." (PMID 25003596, 2014). "In malignant cells, the tumor microenvironment, which contains various inflammatory mediators (e.g., TNFα and GM-CSF), was found to positively regulate MMP12 expression through the activation of NF-κB and AP-1." (PMID 24885469, 2014). "In other regional inflammation-induced lung spontaneous tumor mouse models, overexpression of MMP12 and Api6 in alveolar type II epithelial cells results in Stat3 activation (increased phosphorylation at Y705) in lung epithelial cells." (PMID 23613996, 2013). "Regardless of lung tumor initiated from alveolar type II cells or myeloid cells, CHI3L1 was over-expressed in tumor cells of these MMP12 and Api6-induced spontaneous lung tumor mouse models." (PMID 23613996, 2013). "It has been reported that a protective role of stromal cell-derived MMP-12 in lung metastatic tumour growth is due to inhibition of angiogenesis by angiostatin formation from plasminogen by MMP-12." (PMID 22015555, 2011). "H&E staining at higher magnification in an adjacent tissue slice revealed that the expression of CTS, MMP11 and MMP12 was usually confined to the cytoplasm of a subset of epithelial tumor cells with morphological features of squamous differentiation." (PMID 15989693, 2005). "The biological role of MMP12 in tumor progression is not clearly understood but it is thought to be involved in the degradation of components of the basement membrane." (PMID 15989693, 2005). "Another polymorphism detected in MMP-12 (−82 A>G), also over-expressed in tumours, regulates MMP-12 expression." (PMID 12402142, 2002). "Moreover, in the ex vivo DRG and tumor cell (red) coculture model, MMP12 inhibitor treatment attenuated PNI progression, indicating that both SRC‐1 knockout and MMP12 inhibition effectively alleviated the severity of PNI." (PMID 40985319, 2025). "In contrast, CD206lo IMs (Mmp12) and recMacs were highly enriched in tumor-dense regions." (PMID 40630529, 2025). "However, several studies show that MMP-9 and MMP-12 not only have pro-tumor activity, but they also have anti-tumor activity due to their ability to inhibit angiogenesis in vivo." (PMID 40176865, 2025). "Specifically, the polarization status of macrophages regulated by SRC‐1 changes, and the secretion of MMP‐12 by these macrophages changes accordingly, thereby further affecting the biological characteristics of tumor cells and altering the interaction between the tumor and nerve cells (i.e., PNI)." (PMID 40985319, 2025). "Additionally, MMP12 modulates immune responses by regulating cytokines and chemokines, thereby promoting a tumor-supportive inflammatory environment." (PMID 41465234, 2025). "In lung adenocarcinoma (LUAD), the MMP12 protein level in tumor tissue increases significantly." (PMID 40244135, 2025).
tumor (continued). "In addition, higher expression of MMP1 and MMP12 in patients with tumors post-treatment compared to tumor-free individuals underscores the importance of these markers in predicting treatment response and tumor invasiveness." (PMID 40362553, 2025). "In EAC, MMP12 plays a multifaceted role, not only promoting tumor invasion and metastasis by degrading extracellular matrix components but also contributing to the creation of a microenvironment that favors tumor cell survival and progression." (PMID 39744560, 2025). "Similarly, matrix metalloproteinases MMP1, MMP3 and MMP12 are crucial regulators of tumour angiogenesis, vascular structure, permeability and integrity." (PMID 39161078, 2025). "Moreover, animal experiments confirmed that MMP-12-knockdown CRPC xenograft tumors exhibited reduced tumor growth, and the mechanisms involved the promotion of cancer cell autophagy and the inhibition of lipid catabolism." (PMID 38511770, 2024). "In contrast to other macrophages, TAMs have specific receptors and ligands; for example, TAM can enhance phagocytosis by binding to extracellular matrix metalloproteinase ligands (e.g., MMP-2, MMP-7, MMP-9, and MMP-12), which in turn promotes tumor growth and metastasis." (PMID 38806553, 2024). "Multiple MET markers (CitH3, MPO, MMP2, MMP9, and MMP12) were elevated in macrophages that were co-cultured with tumour cells, but this effect could be rescued by treatment with MET inhibitor (Cl-amidine, a specific PADI4 inhibitor) or GW." (PMID 39025845, 2024). "Furthermore, the tumor invasion-related proteins MMP-7 and MMP-9 were decreased in the context of MMP-12 deficiency." (PMID 38511770, 2024). "MMP2 and MMP12 increase tumor malignancy and promote tumor metastasis and progression." (PMID 37533434, 2023). "Mmp12 and Mmp2 are involved in the generation of the tumor microenvironment." (PMID 36768216, 2023). "MMP12 expression is notably high in GC tissue, escalating with tumor development and metastasis." (PMID 37889539, 2023). "The measurable levels of tumour-localised, immune-cell-derived MMP12 in blood suggest MMP12 as an important biomarker that could complement histopathology-based risk stratification." (PMID 37391708, 2023). "Furthermore, single-cell sequencing was used to determine the distribution of MMP12 in multiple tumor microenvironment cells." (PMID 37601247, 2023). "This difference may result from several factors, including differences in tumor types and stages of development, or even different cells that express MMP12." (PMID 37601247, 2023). "Immunohistology identified MMP12 protein in NSCLC only in tumor cells." (PMID 36650426, 2023). "Several matrix metalloproteinases (MMPs) were up-regulated in tumour samples, namely MMP12 (5.1-fold), MMP14 (2.3-fold) and MMP2 (2.2-fold), which cleave elastin (and insulin), collagen (and other extracellular proteins, such as aggrecan) and certain collagens (and gelatin), respectively." (PMID 37397358, 2023). "MMP12 is linked to reduced overall survival rates in numerous cancers; in UBC, certain genetic polymorphisms of the gene have been shown to increase invasiveness, while higher mRNA expression of MMP12 in tumour tissue has been reported to correlate with higher tumour grade." (PMID 37391708, 2023). "In addition to Hif1a and Vegfa upregulation, MDM-B showed differential expression of Mmp12, Mmp14, and Igf1, which were also part of the tumor microenvironment pathway." (PMID 37858232, 2023). "Furthermore, the macrophage counts and the levels of matrix metalloproteinase (MMP)-12 and angiostatin in tumor cells in the uterus increased compared to the corresponding values in the control group and further increased upon TA treatment." (PMID 35371322, 2022). "At the same time, tumor cells express a large amount of MMP-12 by accumulating macrophages." (PMID 35371322, 2022).
tumor (continued). "KEGG assays revealed MMP12 may influence the activity of several tumor-related pathways, such as the Toll-like receptor signaling pathway, TNF signaling pathway, and IL-17 signaling pathway." (PMID 35265129, 2022). "MMP12 activation in ECFCs degraded uPAR and abolished angiogenesis and tumour growth in melanoma." (PMID 36077754, 2022). "MMP12 is not only expressed in macrophages, but is also found in tumor cells." (PMID 35313071, 2022). "MMP-12 might be expressed by macrophages and tumor cells of epithelial origin, which influences its effect on tumor progression." (PMID 36547091, 2022). "Previous studies demonstrated that MMP12 is involved in tumor metastasis." (PMID 35265129, 2022). "Likewise, injection of ApoSQ inhibited the activation of migration- and invasion-related signaling pathways, including the Smad2/3, FAK, ERK, and Akt pathways, as well as the protein expression of MMP2 and MMP12 in CD326+ tumor cells." (PMID 36241874, 2022). "Turn to MMP12, as one of the members of the matrix metalloproteinases family, it encodes extracellular matrix participating in the (EMT) which was identified as a strictly programmed shift playing a crucial role in tumor invasion and metastasis." (PMID 35831362, 2022). "The correlation among DRP1, FOXM1and MMP12 protein expression in HNC tumor tissues." (PMID 35313071, 2022). "Given this, we speculated that DRP1‐increased metabolic rewiring in tumor cells was required for MMP12 expression." (PMID 35313071, 2022). "Taken together, we speculated that tumor cells release IL-6 to stimulate macrophages to up-regulate MMP12." (PMID 34863141, 2021). "Taken together, our study identified that MMP12 might be a useful tumor biomarker and therapeutic target for ESCC." (PMID 33935718, 2021). "The anti-tumorigenic effect of MMP12 might be due to the generation of angiostatin, which is induced by MMP12 and could prevent tumor angiogenesis." (PMID 33935718, 2021). "Interestingly, in the murine models, MMP12 protects against tumor progression activity, which has been ascribed to the generation of anti-angiogenic peptides due to MMP12 activity." (PMID 34200480, 2021). "There was a poorer degree of tumor differentiation as the expression of MMP-12 went higher." (PMID 33892690, 2021). "We think that knocking out MMP12 in ApcMin/+ mice may lead to partly insulin degradation, and affect insulin sensitivity and the balance of glucose utilization induced by tumor growth." (PMID 34863141, 2021). "Both heavy chains (HCs) of the hinge region can be cleaved sequentially by several proteases of the tumor/inflammatory/infectious microenvironment, including matrix metalloproteinase 12 (MMP12), or immunoglobulin-degrading enzyme from Streptococcus pyogenes (IdeS), impairing Fc-mediated functions." (PMID 32117299, 2020). "Importantly, tumor-associated macrophages (TAMs) secrete membrane-bound or soluble proteases, such as MMP-2, MMP-9, and MMP-12, which are involved in ECM degradation and promote the infiltration of tumor-associated blood vessels." (PMID 31921634, 2019). "The increased availability of Mmp2 and Mmp12 as well as their substrates Col1a1, Col4a1, Col6a1 and LamC2 could indicate that the tumour cells generated foremost collagens, which can be cleaved by these Mmps." (PMID 30603057, 2018). "Notably, it was previously reported that MMP12 increases tumor invasiveness only when expressed by tumor cells whereas its expression by macrophages can be associated with a better prognosis." (PMID 30647853, 2018). "The protein expression of TPX2 and MMP12 was examined by immunohistochemistry in 152 tumor samples." (PMID 30305064, 2018). "To evaluate the potential of MMP12 gene-modified ECFCs as regard to uPAR-dependent tumor invasion and angiogenesis we performed A375 Matrigel invasion and capillary morphogenesis of control human microvascular endothelial cells (HMVEC) in the presence of CM ECFC-MMP12 or CM ECFC-MOCK." (PMID 25003596, 2014).
tumor (continued). "In this study we evaluated the possibility to deliver MMP12 into tumor mass where it could cleave uPAR of tumor cells and ECs." (PMID 25003596, 2014). "Therefore, 82 NPC biopsy specimens were subjected to immunohistochemical (IHC) analysis and the differential expression of MMP12 and hnRNP K between the tumor and normal epithelial tissues were investigated." (PMID 24885469, 2014). "A similar result was observed in the serum of MMP12-induced tumor mice." (PMID 23613996, 2013). "This suggests that elevated serum MMP-12 directly reflects NSCLC tumor biology." (PMID 22509397, 2012). "Thus it is possible that although MMP12 is helpful in enabling tumor cells to invade, its antiangiogenic effects suppress the ability of tumor cells to extravasate and successfully seed metastases in the lung." (PMID 22152016, 2011). "Similarly, Kerkelä and colleagues reported that MMP12 expressed in macrophages in the tumor site correlated with well-differentiated cancer cells." (PMID 15987457, 2005). "The results also confirmed that the expression of autophagy-related proteins in cancer cells was enhanced after MMP-12 silencing, which led to weakened cancer cell malignancy and inhibited tumor growth; these results suggested that MMP-12 may affect the progression of CRPC by regulating autophagy." (PMID 38511770, 2024). "Additionally, the protein levels of CPT1 and CD36 were decreased in MMP-12-knockdown tumor cells." (PMID 38511770, 2024). "MMP3 and MMP12 are both archetypal matrix metalloproteinases (MMPs), a group of protein hydrolases containing active Zn2+ that are involved in many functions related to self-stabilization, such as tissue repair and immune and pathological processes, including tumor, fibrosis, and infection." (PMID 37503314, 2023). "Our conclusion is that MMP12 might play a role in controlling the tumor immune microenvironments." (PMID 35265129, 2022). "IL-6 in the tumor microenvironment are an important determinant of alternative macrophage activation and could induce macrophage M2 polarization, and M2 macrophages can produce MMP12." (PMID 34863141, 2021). "MMP12’s effect on tumor progression may be mediated via its effect on the tumor vasculature." (PMID 34834411, 2021). "Similarly, a high number of tumor-associated macrophages lead to an increased production of angiogenic factors such as VEGF, PDGF, IL-8, TNF-α und bFGF and an enhanced expression of angiogenesis promoting enzymes such as MMP-2, MMP-7, MMP-9 and MMP-12." (PMID 34821752, 2021). "In addition, we observed the increased activity of metalloproteinases (MMP-2 and MMP-12) and levels of the tumor angiogenesis marker VEFG and the lipid peroxidation marker MDA, as well as decreased levels of the non-enzymatic antioxidant GSH and enzymatic antioxidants CAT and GSH-Px in lung tissues." (PMID 31842482, 2019). "These antitumorigenic effects could be based on MMP12-induced decrease of VEGF (vascular endothelial growth factor) level as well as on an increase of Angiostatin level - both are known to play a crucial role in tumor neovascularization." (PMID 27431388, 2016). "In addition, MMP12 is also involved in the cleavage of domain D1 of urokinase-type plasminogen activator cellular receptor, which is responsible for cell migration during tumor invasion and angiogenesis." (PMID 15987457, 2005). "This analysis demonstrated that expression levels of MMP1 and MMP12 were increased in patients with residual tumors post-treatment, whereas RAF1 expression was higher in patients who were tumor-free post-treatment." (PMID 40362553, 2025). "MMP12 expression is regulated positively by MTA2 via AP1 through phosphorylation of the pathway ASK1/MEK3/p38/YB1, leading to tumor cell metastasis." (PMID 41516135, 2025). "We observed that macrophages nearer the central tumor region expressed higher levels of SPP1 and lower levels of MMP12, while macrophages closer to the peripheral tumor region exhibited the opposite expression pattern of SPP1 and MMP12." (PMID 39764138, 2024).
tumor (continued). "Overall, the downregulation of MMP-12 delayed CRPC cell migration and invasion as well as tumor growth by promoting autophagy and inhibiting lipolysis." (PMID 38511770, 2024). "As expected, MMP1, MMP3, MMP12, and SPP1 displayed significantly higher expression in tumor tissues compared to normal samples." (PMID 39596132, 2024). "Our analysis using the HNSCC dataset of TCGA database revealed significantly elevated expression of MMP1, MMP3, MMP12, and SPP1 in tumor tissues compared to normal tissues." (PMID 39596132, 2024). "MMP12 promotes macrophage proliferation via the ERK/P38 MAPK pathway, and the knockdown of MMP12 inhibits the development of some tumor cells." (PMID 37601247, 2023). "The overexpression of miR-708-5p suppresses the tumor invasiveness and migration, thanks to positively targeting Rho-GTPase Rho C effectors (ROCK1 and ROCK2) and Matrix Metallopeptidase 12 (MMP-12), respectively." (PMID 37895198, 2023). "Analysis of the microarray gene expression data from 213 NMIBC and 93 MIBC patient tumour biopsies revealed that MMP7 and MMP12 mRNA expression levels were higher in MIBC." (PMID 37391708, 2023). "To explore the source of MMP7 and MMP12 in UBC, we analysed UBC patient tumour samples that underwent single-cell sequencing and identified epithelial cells as the source of MMP7 and macrophages as the source of MMP12 mRNA transcripts." (PMID 37391708, 2023). "These monocytes and macrophages in luminal tumor hubs upregulate inflammation (MMP12 and MMP9), myeloid cell recruitment (CCL2 and CCL7), and tumor growth–promoting genes (VEGF and EREG)." (PMID 37492581, 2023). "Vegfa+ macrophages exhibited high expression of Spp1, Vegfa, and Mmp12, and enriched in anti-inflammatory pathways, sharing the similarity with the previously termed SPP1+ macrophages, which have an enrichment of tumor angiogenesis and protumorigenic role." (PMID 37115931, 2023). "In line with our report, high MMP12 expression was found in tumor tissues of the HNC sample than in normal tissue in a publicly available cancer database, suggesting that MMP12 expression is involved in cancer progression of HNC." (PMID 35313071, 2022). "MMP12 and MMP9 were related to cancer development, progression, and survival through various pathological processes and play essential roles in tumor invasion and metastasis." (PMID 35741697, 2022). "For discrimination of the normal and tumour sampling zones, we were able to derive an effective gene-based classifying model for molecular abnormality based on a panel of eight genes (MMP1, MMP12, MYO1B, TNFRSF12A, WDR66, LAMC2, SLC16A1 and PLAU)." (PMID 35327656, 2022). "We also provided novel insight into a mechanism by which DRP1 mediated tumor growth and motility via FOXM1/MMP12 axis in HNC." (PMID 35313071, 2022). "In the furthermore bioinformatics analysis, we found that MMP1, MMP3, MMP7, MMP9, MMP12, MMP13 all increased in the tumor as compared with the normal esophageal tissues." (PMID 34559117, 2021). "We also evaluated the protein level of MMPs in our patients and measured the expression level of MMP1–MMP3, MMP7–MMP9, MMP11, MMP12, MMP14, MMP17, MMP19, and MMP28 in their tumor tissue and adjacent normal tissue by Western blot." (PMID 34804973, 2021). "Taken together, these reports also suggest that MMP-12, which affects the parenchymal architecture of the lungs, promotes malignancies and may be a key player involved in lung tissue extracellular matrix degradation, resulting in tumor penetration and metastasis." (PMID 34912233, 2021). "Based on the TCGA and GTEx data, we found that MMP1, MMP3, MMP7, MMP9, MMP12, MMP13 all increased in the tumor as compared with the normal esophageal tissues." (PMID 34559117, 2021). "MMP1, MMP3, MMP7, MMP12, and MMP13 belong to the matrix metalloproteinase family, and MMPs were able to participate in the tumor metastasis process by degrading the ECM." (PMID 34381520, 2021).